BRAF (B-Raf proto-oncogene, serine/threonine kinase)
Diseases named in the same sentence as BRAF in open-access papers (continued):
Sharing a sentence is not in itself a finding about the gene and the disease.
melanoma (continued). "However, despite progress in BRAF-mutant melanoma treatment, the two different approaches approved so far for metastatic disease, immunotherapy and BRAF+MEK inhibitors, allow a 5-year survival of no more than 60%, and most patients relapse during treatment due to acquired mechanisms of resistance." (PMID 33801689, 2021). "The lack of discrimination between BRAF-mt and BRAF-wt melanoma could potentially be explained by activating mutations in the NRAS gene in BRAF-wt melanoma." (PMID 33915880, 2021). "We showed by both in silico and in vitro analyses that miR-129-5p is induced by BRAFi or MEKi treatment exclusively in melanoma cell lines with BRAF mutations, and not in primary normal human epidermal melanocytes (NHEMs), BRAF wildtype melanoma cells or BRAFi resistant melanoma cells." (PMID 34063443, 2021). "Additionally, specific inhibition of EZH2 induces miR-129-5p expression in BRAF mutated melanoma cell lines, independent from their BRAFi response status, while BRAF wildtype cells and normal melanocytes show no changes of expression." (PMID 34063443, 2021). "Importantly, ROS levels were increased upon MAPK pathway blockade in BRAF-driven melanoma cells using a BRAF inhibitor, which may be exploited as a strategy to induce caspase-independent apoptosis programs." (PMID 34298710, 2021). "Additionally, in mouse melanoma models, BRAF inhibitors reduced the number of regulatory T cells and MDSCs, with a simultaneous increase in the activity of antigen-presenting DCs, while anti-MEK therapy decreased the mortality of overstimulated effector T lymphocytes." (PMID 33171792, 2020). "However, as NF1 mutations can be found in melanomas with concurrent BRAF or NRAS hotspot mutation, a three-group classification of melanoma (mutant BRAF, mutant RAS, non-BRAFmut /non-NRASmut) has been proposed." (PMID 32850962, 2020). "Although targeted therapy and immunotherapy benefit advanced melanoma patient treatment, BRAFi (BRAF inhibitor) resistance and the lower response rates or severe side effects of immunotherapy have been observed, therefore, it is necessary to develop novel inhibitors for melanoma treatment." (PMID 32021565, 2020). "The other three subtypes, as well as melanoma of unknown primary, were dominated by driver mutations in the genes of the cell cycle control (CDKN2A) and the RTK/RAS signaling pathway (BRAF, NRAS, ERRB2)." (PMID 32825510, 2020). "Although melanoma tumour tissue is more often accessible, ctDNA can be used to quickly identify theranostic BRAF mutations, without going through the various preanalytical steps commonly performed on tumour tissue (formalin fixation, paraffin embedding, preparation of thick sections)." (PMID 32664549, 2020). "Ptch1 is endogenously expressed in various melanoma cell lines, and we found that decreased Ptch1 expression strongly inhibited the efflux of doxorubicin, indicating that Ptch1 is involved in doxorubicin efflux in melanoma cells with or without the BRAF mutation." (PMID 32526884, 2020). "However, this study also highlights the variability in metabolic rewiring between melanomas with different oncogenic drivers and suggests that mutant BRAF and mutant NRAS may utilize different metabolic pathways for survival benefits." (PMID 32046099, 2020). "The Idylla BRAF mutation assay performed on the Idylla molecular diagnostics platform is an allele-specific real-time PCR-based technique, which has got CE-IVD certification for the qualitative detection of the V600E/E2/D and V600K/R/M mutations in FFPE samples of malignant melanoma." (PMID 32879641, 2020). "Interestingly, our results suggest that BRAF V600E is a promising biomarker of prognosis in AJCC stage II melanoma patients, which may help to improve the personalized medical care and survival of melanoma patients." (PMID 32168325, 2020).
melanoma (continued). "BRAF p.G593D has been identified in solid cell nest hyperplasia in association with BRAF p.V600E mutated PTC, while the BRAF p.R603Q and p.S607F mutations were reported in nevi, in association with BRAF p.V600E mutated melanomas, similar to what we observed in our cases." (PMID 32059434, 2020). "Furthermore, the BRAF alteration is often associated with mutations of PTEN, an inhibitor of the PI3 kinase/Akt1 pathways, which in turn causes an increased activation of PI3K/Akt1 and can further enhance melanoma progression." (PMID 32630674, 2020). "Therefore, sorafenib is mainly used for renal cell carcinoma and hepatocellular carcinoma, and its effect on melanoma mainly caused by a BRAF mutation is not good." (PMID 32476297, 2020). "These non-canonical mutation classes include NRAS Q61R and BRAF V600K and V600E, which are among the most common driver mutations in melanoma, indicating that mutations caused by atypical photoproducts may promote melanomagenesis." (PMID 33207206, 2020). "This proposed module could lead to the enhanced BRAF inhibitor resistance in melanoma patients." (PMID 32565808, 2020). "Moreover, paradoxical MAPK activation, induced by BRAF inhibitors in genetically “normal” stromal cells, promotes a “therapy-resistant” microenvironment: Intravital imaging analyses conducted in melanoma have shown major paradox MAPK reactivation, especially in areas with high stromal density." (PMID 33036192, 2020). "The melanoma treatment landscape changed in 2011 with the approval of the first anti-cytotoxic T-lymphocyte-associated protein (CTLA)-4 checkpoint inhibitor and of the first BRAF-targeted monoclonal antibody, both of which significantly improved overall survival (OS)." (PMID 32894202, 2020). "A phase 2 trial, evaluating the activity and the efficacy of trametinib in patients with advanced melanoma not mutated in V600 BRAF (NCT02296112), could help to shed some light on the role of MEK inhibitors in this rare subset of melanoma." (PMID 33233603, 2020). "Because BRAF inhibitors also induce PGC-1α, a regulator of mitochondrial biogenesis that in turn causes OXPHOS upregulation, combining BRAF inhibitors and phenformin could have reduced the proliferation of BRAF-mutant melanoma cells and contribute to tumor regression in that study." (PMID 33178201, 2020). "Non-CSD melanoma is associated with moderate mutation burdens, including BRAF V600E mutations." (PMID 32462000, 2020). "BRAF inhibitors dramatically improved response rate and survival compared with standard chemotherapy in patients with BRAF-mutated melanoma, but these benefits were not durable, and most patients developed progressive disease as a result of resistance development." (PMID 33003483, 2020). "In BRAFi-resistant melanoma, the upstream reactivation of signal transduction from the cell membrane to MAPK/ERK kinases is caused by the overexpression of tyrosine kinase receptors, which leads to cell division by the activation of ARAF and CRAF kinases instead of BRAF." (PMID 32605090, 2020). "Furthermore, it has been reported in in vivo mouse models that slow cycling melanoma cells which adaptively resist to BRAF/MEK inhibitors (MAPKi) are also capable of reentering the cell cycle and give rise to highly metastatic subclones that invade different tissues." (PMID 33202944, 2020). "We also domnostrated that the role of LINC00520 in melanoma cells is independent of BRAF mutation." (PMID 32466797, 2020). "Another possibility could be the use of agents targeting mitochondrial ATP, which has also already showed promising results in melanoma cells with acquired resistance to BRAF inhibitors and should be tested in melanoma cell lines with acquired resistance to MEK or cKIT inhibitors." (PMID 32455924, 2020).
melanoma (continued). "While the efficacy of signal transduction inhibitors that target BRAF-V600E/K mutation is well described for patients with melanoma, treatments for patients that do not harbor a BRAF-V600E/K mutation are limited to immunotherapy and lack other clinical options." (PMID 32764384, 2020). "For example, BRAF inhibitors are very effective against melanoma with BRAF V600E/K mutations, but they are not effective for colorectal cancers bearing the same BRAF V600E mutation, suggesting that mutated BRAF is not fully responsible for the proliferation of these cancers." (PMID 32069833, 2020). "Furthermore, acquired resistance to BRAF inhibitors in melanoma was dependent on dynamic regulation of KRAS expression and could be overcome by KRAS inhibition." (PMID 31906510, 2020). "However, mutations in BRAF are early and not sufficient to induce melanoma: there is a high frequency of these mutations in benign nevi (including congenital, intra-dermal, and dysplastic), and it seems that additional genetic events are necessary." (PMID 32695793, 2020). "Another clinical study reported the results of a randomized, double-blind, phase III trial, which showed that nivolumab improves overall survival in patients with advanced melanoma without B-Raf proto-oncogene, serine/threonine kinase (BRAF) mutations compared with dacarbazine." (PMID 32522267, 2020). "The ability of BRAF inhibitors (and MEK inhibitors) to modify the tumour microenvironment and enhance anti-tumour immune responses in BRAF-mutated melanoma supports the idea that a combination of targeted therapy and immunotherapy could provide greater anti-tumour activity." (PMID 32645969, 2020). "Importantly, HTDS identified novel drug combinations to target BRAF-resistant melanoma." (PMID 31857724, 2020). "No BRAF mutations were detected in the 9 previously reported cases of primary malignant melanoma of the lung or our case; therefore, primary malignant melanoma of the lung might be a form of de novo cancer, rather than arise from melanocytic nevus." (PMID 32028967, 2020). "In the present study, we have, thus, investigated if other extracellular signals might trigger NRP1-dependent tumor malignancy, and found that a relatively poorly studied NRP1-ligand, Galectin-1 (Gal-1), is upregulated in melanoma cells upon the onset of resistance to BRAF-targeted drugs." (PMID 32784465, 2020). "Around 50% of melanoma patients carry mutations in the BRAF gene and around 30% of patients in the NRAS gene resulting in an over-activation of the mitogen-activated protein kinase (MAPK) pathway, making this signalling cascade one of the most important targets for melanoma therapy." (PMID 32063604, 2020). "A high percentage of melanoma patients do not respond to BRAFi therapy, although they carry an activating BRAF mutation; these patients are defined as primarily, intrinsically or innately resistant to targeted therapies aimed at downregulating or suppressing the MAPK signaling pathway." (PMID 33419275, 2020). "Besides, application of BRAF inhibitors could improve outcomes of melanoma, colorectal cancer and non-small cell lung cancer patients 50-52." (PMID 33162799, 2020). "However, the results of our study enable us to suppose that both vanicosides could affect the viability of malignant melanoma cells by inhibiting the BRAF(V600E) and MEK1 kinases." (PMID 32610527, 2020). "The clinical implementation of BRAF and MEK inhibitor therapies (including dabrafenib and trametinib and vemurafenib and cobimetinib) has resulted in dramatic improvements in OS and progression-free survival (PFS) rates in patients with BRAF-mutated advanced melanoma." (PMID 32605090, 2020). "When a metastatic tissue sample is not available, the analyses may be performed on samples obtained from lymph node metastases or primary tumor since a high concordance of the BRAF status between primary melanomas and their metastatic lesions has been demonstrated." (PMID 32695793, 2020).
melanoma (continued). "This suggested that the role of LINC00520 in melanoma cells is independent of BRAF mutation." (PMID 32466797, 2020). "Reports are suggesting that overactivation of the PI3K/AKT/mTOR pathway might contribute to the survival of melanoma cells upon BRAF V600E inhibition and that dual targeting of advanced human cancers with inhibitors of the PI3K/AKT/mTOR and RAF/MEK/ERK pathways might be beneficial." (PMID 32531927, 2020). "Consequently, targeting AEBP1 may prove to be an effective therapy for drug resistance in melanoma patients subjected to BRAF inhibitors." (PMID 32565808, 2020). "It appears that the mutational landscape of mucosal melanoma points out to a distinct pattern between the upper and lower regions of MM commitment with SF3B1 and KIT presenting higher mutation rates than the common drivers of cutaneous melanomas, namely BRAF and NRAS." (PMID 31949210, 2020). "The mutational status of metastatic lesions cannot easily be tested because melanoma metastasizes to subcutaneous and superficial lymph nodes, visceral areas, and deep lymph nodes; therefore, in such cases, whether BRAF/MEK inhibitors are suitable for patients with melanoma is unclear." (PMID 33150263, 2020). "As it is known, a requirement for administration of BRAFi/MEKi is the identification of a BRAF mutation in specific melanoma samples, which, however, may not represent the current somatic mutation status or tumor heterogeneity." (PMID 32695793, 2020). "Our data indicated higher B-cell CLL/lymphoma 2 (BCL2) expression in melanoma without BRAF hotspot mutations, suggesting that BH3 mimetics, such as ABT-199 (venetoclax, a small molecule against BCL2), may be a potential therapeutic option for these patients." (PMID 32764384, 2020). "In melanoma, CD73 expression is influenced by sample type (e.g., primary, metastatic, or relapse tissue); therapy treatment; and presence of activating MAPK (e.g., BRAF) mutations, mitogenic and inflammatory signals [e.g., hepatocyte growth factor (HGF) and TNF-α], and necrosis." (PMID 32351498, 2020). "Since the MAPK pathway is frequently activated in melanoma via mutation of BRAF or NRAS and p300 acetyl transferase activity is enhanced by MAPK-mediated phosphorylation in keratinocytes, we asked whether MAPK signaling activates acetylation in melanoma." (PMID 32531202, 2020). "Therefore, we investigated if STING agonists such as the newly developed dimeric aminobenzimidazole (diABZI) could sensitize melanoma cells to the clinically used BRAF inhibitors." (PMID 32477956, 2020). "In addition, because increased IGF1R expression levels were identified in the nCounter PanCancer Pathway Panel for Gene Expression, in both HAT1-knockdown and HAT1-KO BRAF-mutant melanoma cells, we analyzed the mRNA levels as well as protein levels of phospho- and total IGF1R in these samples." (PMID 32371878, 2020). "Therefore, our findings may have clinical implications and enable repurposing of Ponatinib in melanoma and other oncogenic BRAF-dependent tumors, more likely in a combination therapy with a MEK inhibitor or immunotherapy." (PMID 32873792, 2020). "In agreement with our findings, it has been suggested that because of the loss of the negative feedback loop between p38 and ERK both pathways could be activated simultaneously in melanoma that may contribute to the decreased p-ERK level upon p38 inhibition in BRAF mutant melanoma cells." (PMID 32414111, 2020). "Finding targets to prevent the degradation of metastatic suppressors could be an additional tool of counteracting resistance in metastatic cancer cells, therefore, p38 inhibitors can be considered as a putative therapeutic option for the treatment of BRAF mutant melanoma metastasis." (PMID 32414111, 2020). "Moreover, NF1 together with BRAF and NRAS has been found significatively mutated in melanoma." (PMID 32850962, 2020).
melanoma (continued). "To determine whether the miR-146a downregulation and COX2 upregulation observed in BRAF/MEKi-resistant melanoma cell lines in vitro also occurred in vivo in melanoma patients, we analyzed tumor samples surgically excised for local treatment from patients undergoing BRAF/MEKi therapy." (PMID 32967672, 2020). "Interestingly, genomic analysis of MUPs has found they have a mutational profile more similar to cutaneous melanoma than that of mucosal melanoma or CNS melanoma, including mutations in BRAF and NRAS, suggesting that regression or misdiagnosis of a previous cutaneous lesion was the primary melanoma." (PMID 32652526, 2020). "Importantly, we found that HI-511, a novel dual-target inhibitor against AURKB and BRAF V600E, suppresses both vemurafenib-sensitive and vemurafenib-resistant melanoma growth in vitro and in vivo by inducing apoptosis and mediating the inhibition of the BRAF/MEK/ERKs and PI3K/AKT signaling pathways." (PMID 32863956, 2020). "Although the administration of a BRAF inhibitor (such as vemurafenib) improves patient survival, approximately 70% of patients acquire drug resistance within 6 months; therefore, overcoming drug resistance is a challenge for melanoma-targeting therapeutic treatments." (PMID 32021565, 2020). "We know that V600E mutant BRAF melanoma cells are strictly addicted to glycolysis, the so-called Warburg effect, thus it was possible that a reduction of the glycolytic pathway may have a role in the decreased proliferation and motility of OLEO-treated melanoma cells." (PMID 32013090, 2020). "Therefore, a dual-target inhibitor for both AURKB and BRAF V600E might be an effective approach for overcoming drug-resistant melanoma." (PMID 32863956, 2020). "Indeed, several studies have found relatively homogeneous BRAF V600E expression in melanoma." (PMID 32143442, 2020). "Moreover, evidence of cooperation between BRAF activating mutations and PTEN loss in melanoma development was found, suggesting that the activation of MAPK and AKT pathways may be required for melanoma progression." (PMID 32850962, 2020). "While mutations of BRAF and NRAS are the most commonly described in melanoma cells, a number of less common aberrations have been identified, which might also provide new therapeutic opportunities and identification of new targets continue to increase therapeutic options." (PMID 32575838, 2020). "However, BRAFV600E mutant melanomas treated with BRAF kinase inhibitors develop resistance." (PMID 32626712, 2020). "Importantly, they also found that HI-511, a dual-target inhibitor against both AURKB and BRAF V600E, suppresses both drug-sensitive and -resistant melanoma development by inducing apoptosis and mediating the inhibition of the BRAF/MEK/ERKs and PI3K-AKT signaling pathways." (PMID 33490091, 2020). "The assumption was made that melanoma cells with such mutations would continue to divide, as they have an advantage in respect to survival and proliferation when their metabolism is not affected by BRAF inhibition." (PMID 32605090, 2020). "Targeting BRAF (v-raf murine sarcoma viral oncogene homolog B1), MEK (mitogen-activated protein kinase), the immune checkpoint receptors cytotoxic T-lymphocyte-associated antigen 4 (CTLA-4), and programmed cell death PD-1 has improved the overall survival of melanoma patients." (PMID 32052079, 2020). "Thus, the mechanical adaptation of melanoma cells to BRAF inhibition may generate, in the long run, a pool of AXLhigh-resistant cells." (PMID 32466585, 2020). "Taken together, our data suggest that in patients with BRAF-mutant melanoma, the combination of BRAFi with miR-126-3p mimics could represent a novel therapeutic approach to counteract the development of resistance as well as to impair growth and metastasis of tumors become unresponsive to BRAFi." (PMID 31227006, 2019). "Moreover, GW3965 was also effective in BRAF inhibitor‐resistant melanoma models." (PMID 31468706, 2019).